CCRL2 (C-C motif chemokine receptor like 2)
Diseases named in the same sentence as CCRL2 in open-access papers (continued):
Sharing a sentence is not in itself a finding about the gene and the disease.
melanoma (4 papers, 2021 to 2025). A malignant, usually aggressive tumor composed of atypical, neoplastic melanocytes. "In a previous study, we demonstrated that the loss of Ccrl2 in the host accelerates papilloma development in a chemical model of skin carcinogenesis, whereas CCRL2 overexpression in B16 melanoma or LLC cells delays tumor graft growth in vivo." (PMID 40867595, 2025). "To elucidate the molecular mechanisms underlying the phenotypic differences observed in B16 melanoma spheroids, we performed bulk RNA sequencing of B16, CCRL2-overexpressing, and CCRL2-knockout spheroids." (PMID 40867595, 2025). "In contrast, B16 melanoma cells exhibited distinct spheroid phenotypes depending on CCRL2 expression." (PMID 40867595, 2025). "Together, these findings demonstrate that CCRL2 governs transcriptional programs in melanoma cells through bidirectional modulation of TLR4 and IFNAR signaling pathways." (PMID 40867595, 2025). "To evaluate the role of CCRL2 in tumor cell survival and clonogenic potential, we performed colony formation assays using B16 melanoma and LLC cell lines." (PMID 40867595, 2025). "In murine models of lung tumor and melanoma, CCRL2 is protective against tumor progression by promoting NK cell activation and macrophage-T cell immunity, respectively." (PMID 36662882, 2023). "Dpletion of CCRL2 in mice enhanced melanoma tumor growth via impaired antitumor immunity and reduction of T cell responses." (PMID 37274231, 2023). "Following the graft of B16-F0 melanoma or Lewis lung carcinoma cells under the back skin, Ccrl2 KO mice developed smaller tumors than WT mice." (PMID 34638484, 2021). "Expression of CCRL2 was described in many types of human tumors such as melanoma, neuroblastoma, prostate, breast, and gastric cancer." (PMID 34638484, 2021). "This bidirectional regulatory pattern was particularly evident in STAT1 and IRF3 downstream signatures, further supporting the hypothesis that CCRL2 serves as a key modulator of innate immune gene programs in melanoma cells." (PMID 40867595, 2025). "Together, these findings demonstrate that CCRL2 expression strongly influences the structural organization of B16 melanoma spheroids, independent of external culture conditions." (PMID 40867595, 2025). "Although CCRL2 did not affect proliferation, migration, or clonogenicity in B16F0 melanoma and LLC cells, it significantly influenced spheroid morphology in B16F0 cells." (PMID 40867595, 2025). "Acting through receptor crosstalk rather than intrinsic signaling, CCRL2 orchestrates the balance between interferon-mediated and MAPK-driven immune responses, ultimately shaping both the structural and immunological properties of melanoma spheroids." (PMID 40867595, 2025).
ovarian carcinoma (4 papers, 2017 to 2022). A malignant neoplasm originating from the surface ovarian epithelium. "The prolonged OS of patients with high expression of CMKLR1 and CCRL2 clearly suggested an anti-tumoral effect of serum chemerin being activated in ovarian cancer tissue." (PMID 31370263, 2019). "In conclusion, with regard to tumor expression of chemerin receptors, this adipokine is suggested to exert a tumor-suppressive role in ovarian cancer via binding to CMKLR1 and CCRL2." (PMID 31370263, 2019). "Chemerin (RARRES2 [retinoic acid receptor responder 2] and TIG2 [tazarotene induced gene 2]), is purified from the ascetic fluids of ovarian cancer patients and has been shown to be a natural ligand for G protein-coupled receptor-1 (GPR-1) and chemokine C-C motif receptor-like-2 (CCRL-2)." (PMID 29190935, 2017). "RARRES2 levels negatively, whereas CMKLR1 levels positively influenced both OS and progression-free survival (PFS) of ovarian cancer patients, and GPR1 and CCRL2 levels did not affect patients’ OS or PFS." (PMID 36009457, 2022). "First, we characterized the employed ovarian cancer cell lines OVCAR-3, OAW-42 and SK-OV-3 with regard to their expression of the receptors CMKLR1 and GPR1, which are known (unlike CCRL2) to affect intracellular signaling and thus are relevant for this in vitro study." (PMID 36077645, 2022).
acute myeloid leukemia (3 papers, 2017 to 2025). Acute myeloid leukemia (AML) is a group of neoplasms arising from precursor cells committed to the myeloid cell-line differentiation. "One study revealed the critical role of CCRL2 in secondary acute myeloid leukemia." (PMID 37274231, 2023).
neuroblastoma (3 papers, 2017 to 2021). Neuroblastoma (NB) is the most common solid, extracranial childhood tumor. "Furthermore, expression of CMKLR1 and CCRL2 was found to be upregulated in neuroblastoma cohorts in comparison to benign counterparts, while increased CCRL2 expression was correlated to poor prognosis." (PMID 30555465, 2018). "Additionally, we observed that expression of chemerin receptor CCRL2 was elevated in the neuroblastoma cohorts compared to neurofibroma and neural crest, and that high expression of CCRL2 correlated with a poor survival prognosis." (PMID 29221117, 2017). "Although we were able to detect CCRL2 mRNA in neuroblastoma cell lines (data not shown), the role of CCRL2 in neuroblastoma was not addressed in the present study." (PMID 29221117, 2017).
Obesity (3 papers, 2022 to 2025). Accumulation of substantial excess body fat. "Additional studies have demonstrated that CCRL2 deficiency worsens obesity and insulin resistance by increasing macrophage infiltration into adipose tissue." (PMID 37122736, 2023). "In another integrative methylome–transcriptome analysis, seven key genes were identified—CCRL2, GPT, LGALS12, PC, SLC27A2, SLC4A4, and TTC36—that were hypermethylated in obesity and concurrently showed reduced expression." (PMID 41303351, 2025). "In summary, we successfully identified seven key genes, namely, CCRL2, GPT, LGALS12, PC, SLC27A2, SLC4A4, and TTC36, which are involved in obesity occurrence and development likely through the immune microenvironment." (PMID 36313453, 2022). "In this study, by analyzing three GEO datasets and verifying in 24 patients, we identified that CCRL2, GPT, LGALS12, PC, SLC27A2, SLC4A4, and TTC36 might be the key genes that play an important role in obesity pathogenesis." (PMID 36313453, 2022).
Oral ulcer (3 papers, 2019 to 2025). Erosion of the mucous mebrane of the mouth with local excavation of the surface, resulting from the sloughing of inflammatory necrotic tissue. "For example, the mutation of rs11266744 altered the m6A modification of CCRL2, regulated the expression of the local gene CCRL2, and thereby participated in the pathogenesis of oral ulcers." (PMID 41444670, 2025). "Further, an analysis of the relationship between loci in CCRL2 and different diseases showed that rs11266744 was most closely associated with oral ulcers." (PMID 35958581, 2022). "Additional variants in this region (e.g. rs4493469 near CCR3 and rs34390431 near CCRL2) also showed strong evidence for an association with mouth ulcers after clumping." (PMID 30837455, 2019). "For instance, SNP rs11266744 participated in oral ulcer pathogenesis by regulating the local expression of CCRL2." (PMID 41444670, 2025). "In summary, by analyzing genome-wide association studies, this study showed that m6A modification may be involved in the pathogenesis of oral ulcers and CCRL2 may be the targeted gene." (PMID 35958581, 2022). "The SNP rs11266744 (p=2.00E-27) may regulate the expression of the local gene CCRL2, thereby participating in the pathogenesis of oral ulcers." (PMID 35958581, 2022). "Therefore, the abnormal expression of the gene CCRL2 in mucosal tissues is very likely to trigger inflammation and then induce the occurrence of oral ulcers, and m6A-SNPs play an important role in this process." (PMID 35958581, 2022). "Among them, the expression of inflammation-related genes such as CCRL2, HLA-C, GSDMB, HLA-DPB1, and MAPT increased in patients with oral ulcers." (PMID 35958581, 2022). "In addition to inflammation-related genes such as CCRL2, the role of non-inflammation-related genes in oral ulcers is also of interest." (PMID 35958581, 2022).
papilloma (3 papers, 2021 to 2025). A benign epithelial neoplasm that projects above the surrounding epithelial surface and consists of villous or arborescent outgrowths of fibrovascular stroma. "Loss of function of Ccrl2 accelerated the development of papillomas in a chemical model of skin carcinogenesis (DMBA/TPA), whereas the growth of B16 and LLC tumor cell grafts was delayed." (PMID 34638484, 2021). "Ccrl2 KO mice developed the first papillomas by week 11 of the treatment, while they appeared only at week 15 in the control group." (PMID 34638484, 2021). "Indeed, the proportion of large papillomas (>3 mm) and carcinomas reached 25.4% in Ccrl2 KO mice versus 18.9% in control mice by the end of the experiment." (PMID 34638484, 2021).
AIDS (2 papers, 2011 to 2025). A syndrome resulting from the acquired deficiency of cellular immunity caused by the human immunodeficiency virus (HIV). "In humans it has been reported that CCRL2 polymorphisms are associated with AIDS progression, and further analysis suggested the role of the CCRL2 p.Y167F missense variant in Pneumocystis pneumonia (PCP) infections." (PMID 39811276, 2025). "CCRL2-167F was associated with strong accelerated progression to AIDS, resulted almost entirely from rapid development of the AIDS-defining disease PCP." (PMID 22046140, 2011). "Moreover, a previous report linked CCRL2 point mutations with AIDS progression and Pneumocystis pneumonia (PCP) infections." (PMID 39811276, 2025). "The strongest new association was for CCRL2-Y167F with progression to clinical AIDS." (PMID 22046140, 2011). "In addition to the known CCR5 and CCR2 associations, significant associations were identified for CCR3, CCR8, and CCRL2 on progression to AIDS." (PMID 22046140, 2011). "Further analysis indicated that CCRL2-167F was specifically associated with more rapid development of pneumocystis pneumonia (PCP) (RH = 2.84, 95% CI 1.28–6.31) among four major AIDS–defining conditions." (PMID 22046140, 2011). "Significant associations with differential progression to clinical AIDS were observed for CCR3 -255C (RH = 0.62, P = 0.009), for CCRL2-243V (RH = 0.66, P = 0.03), and for CCRL2-167F (RH = 1.89, P = 0.0003) and for CCR8-27G (RH = 1.44, P = 0.004)." (PMID 22046140, 2011). "Genotypes of exonic polymorphisms in chemokine coreceptor genes CCR3, CCRL2 and CXCR6 on Chromosome 3p21 and in CCR8 and CX3CR1 on 3p22 were tested for their genetic influence on AIDS progression." (PMID 22046140, 2011). "A multivariate survival analysis pointed to a previously undetected association of a non-conservative amino acid change F167Y in CCRL2 with AIDS progression: 167F is associated with accelerated progression to AIDS (RH = 1.90, P = 0.002, corrected)." (PMID 22046140, 2011). "In an explanatory analysis, we tested whether CCRL2- Y167F affects AIDS progression through a specific AIDS-defining illness." (PMID 22046140, 2011). "The association of CCRL2 with AIDS and PCP is unique as CCRL2 has not been shown to serve as a coreceptor for HIV-1." (PMID 22046140, 2011).
allergic asthma (2 papers, 2022 to 2025). A asthma with a basis in a pathological type I hypersensitivity reaction. "Studies have shown that CCRL2 mediates the migration of inflammatory cells and exerts pro-inflammatory effects in mouse models of RA and allergic asthma." (PMID 40502627, 2025). "It is possible that OA exerts its inhibitory effect on CCRL2 expression in lung DCs and subsequently contributes to the resistance to allergic asthma by decreasing the migration of lung DCs into mediastinal lymph nodes." (PMID 35743888, 2022).
asthma (2 papers, 2011 to 2021). "Data obtained in ovalbumin-induced asthma model in CCRL2 deficient mice show that CCRL2 supports the migration of antigen-laden lung DC into the mediastinal lymph nodes and this step is required for the full-blown disease manifestation." (PMID 21272574, 2011).
breast tumor (2 papers, 2019 to 2022). "CCR3 and CX3CR1 were differentially expressed between Black versus White, and CCR6, CCRL2, and CXCR4 between Asian versus White breast tumors." (PMID 35754051, 2022).
glioma (2 papers, 2020 to 2021). A benign or malignant brain and spinal cord tumor that arises from glial cells (astrocytes, oligodendrocytes, ependymal cells). "CCL2 expression pattern was very similar to that of CCRL2, and significantly increased with higher glioma tumor grade, whereas CCL5 expression exhibited an inverse relationship and its level decreased with increasing tumor grade." (PMID 32456359, 2020). "It was demonstrated that CCRL2 expression level was significantly elevated in both low grade and high grade human glioma patients and cell lines." (PMID 32456359, 2020). "Increased CCRL2 expression was described in glioma tumors and glioma cell lines." (PMID 34638484, 2021). "We also depict various chemokine/receptor axes, such as CXCL8-CXCR1/2, CXCL12-CXCR4, CXCL16-CXCR6, CX3CL1-CX3CR1, CCL2-CCR2, and CCL5-CCR5 of special importance in gliomas, as well as atypical chemokine receptors ACKR1-4, CCRL2, and PITPMN3." (PMID 32456359, 2020).
Salmonella Infections (2 papers, 2021 to 2025). Infections with bacteria of the genus SALMONELLA. "Up regulation of hnRNPM after 4 hours of Salmonella infection stimulated the chemokine receptor CCRL2, the regulator of NF-κB (NFKBIZ) pathway." (PMID 41026719, 2025).
atherosclerosis (1 paper, 2014). A disease characterized by the build-up of fatty material and calcium deposition in the arterial wall resulting in partial or complete occlusion of the arterial lumen. "These genes included the chemokines CCL5, CXCL10, CCL8, CXCL9, CCRL2, which were also up-regulated in carotid or coronary human plaques, as shown here, and together reflect pro-atherogenic responses in human atherosclerosis." (PMID 25196434, 2014).
diabetes (1 paper, 2019). "Targeting CCRL2 and/or ChemR23 could be useful for treating neuropsychological deficits in offspring of dams with diabetes in pregnancy." (PMID 31733653, 2019).
endothelial dysfunction (1 paper, 2022). In vascular diseases, endothelial dysfunction is a systemic pathological state of the endothelium (the inner lining of blood vessels) and can be broadly defined as an imbalance between vasodilating and vasoconstricting substances produced by (or acting on) the endothelium. "Specifically, we identified CCRL2, LGALS9, and PLCB2 as key genes associated with abnormal ESS and AS and initially explored the roles of these genes in endothelial dysfunction and AS, thus highlighting the possibility of new preventive and therapeutic strategies for AS by targeting these genes." (PMID 35990248, 2022).
erythroleukemia (1 paper, 2025). Acute erythroid leukemia characterised by the presence of at least 50% erythroid precursors and at least 20% myeloblasts in the bone marrow.
metastatic prostate carcinoma (1 paper, 2017). A carcinoma that arises from the prostate gland and has spread to other anatomic sites. "Our results show that metastatic prostate cancer cell line PC-3 significantly expresses higher mRNA and protein levels of CCRL2 compared with non-tumorigenic PWR-1E." (PMID 29497024, 2017).
multiple myeloma (1 paper, 2018). "We found that chemerin is expressed by stromal cells and preadipocytes, whereas its receptor CCRL2 is expressed by primary myeloma cells, suggesting a paracrine signaling loop between bone marrow stromal cells/adipocytes and myeloma cells." (PMID 29946468, 2018). "Stromal cells obtained from myeloma patients and pre-adipocytes produce chemerin, whereas the receptors CCRL2 and CMKLR1 are expressed by myeloma cells." (PMID 29946468, 2018). "Interestingly, primary myeloma cells expressed more CCRL2 and CMKLR1 mRNA compared with multiple myeloma cell lines." (PMID 29946468, 2018).
periodontitis (1 paper, 2024). An acute or chronic inflammatory process that affects the tissues that surround and support the teeth. "ACSL5, NLRP12, CCRL2, and CEACAM3 were identified as hub genes and diagnostic genes in both PCOS and periodontitis." (PMID 38167332, 2024). "Through RF of the identified hub genes (ACSL5, NLRP12, CCRL2, and CEACAM3), pathways that activate the immune system were implicated in PCOS and periodontitis." (PMID 38167332, 2024). "The 4 hub genes ACSL5, NLRP12, CCRL2, and CEACAM3 may be diagnostic genes for PCOS and periodontitis." (PMID 38167332, 2024). "Genes such as ACSL5, NLRP12, CCRL2, and CEACAM3 were identified as the molecular link between PCOS and periodontitis." (PMID 38167332, 2024). "Intersection of the candidate genes 1 and 2 yielded 4 hub genes (ACSL5, NLRP12, CCRL2, and CEACAM3) involved in both PCOS and periodontitis." (PMID 38167332, 2024). "Additionally, the AUCs of ACSL5, NLRP12, CCRL2, and CEACAM3 in the periodontitis training dataset were 0.771, 0.819, 0.708 and 0.785, respectively, which also suggested the diagnostic values of 4 hub genes on periodontitis were strong." (PMID 38167332, 2024).
preeclampsia (1 paper, 2024). Preeclampsia is a hypertensive disorder of pregnancy that is characterized by new-onset hypertension with proteinuria presenting after 20 weeks of gestation, and depending on mild or severe forms may initially present with severe headache, visual disturbances, and hyperreflexia.
pulmonary fibrosis (1 paper, 2023). Chronic progressive interstitial lung disorder characterized by the replacement of the lung tissue by connective tissue, leading to progressive dyspnea, respiratory failure, or right heart failure. "CCRL2 was downregulated in IPF samples, bleomycin-induced pulmonary fibrosis, and TGFβ1-induced fibroblast." (PMID 37122736, 2023).
pulmonary hypertension (1 paper, 2020). Increased pressure within the pulmonary circulation due to lung or heart disorder. "Alteration in chemerin signaling has already been linked to other pro-inflammatory conditions or cytokines (including TNF-α, IL-1β, and IL-6) upregulating CMKLR1 and CCRL2 which are also known to play crucial roles in pulmonary artery remodeling in pulmonary hypertension." (PMID 32848866, 2020).
rheumatoid arthritis (1 paper, 2025). A chronic, systemic autoimmune disorder characterized by inflammation in the synovial membranes and articular surfaces. "Similarly, CCRL2 expression is upregulated in synovial neutrophils of patients with rheumatoid arthritis compared to healthy controls." (PMID 40181978, 2025).
Sepsis (1 paper, 2016). Sepsis is defined as life-threatening organ dysfunction caused by a dysregulated host response to infection. "Cmklr1 mRNA was significantly decreased in both CD and HFD mice following sepsis (p = 0.001 and p < 0.001, respectively), while Ccrl2 mRNA was increased (p = 0.024 and p = 0.012, respectively)." (PMID 26873079, 2016).
triple-negative breast carcinoma (1 paper, 2022). An invasive breast carcinoma which is negative for expression of estrogen receptor (ER), progesterone receptor (PR), and human epidermal growth factor receptor 2 (HER2). "CCRL2 was higher in Asian than White patients with triple negative breast cancer." (PMID 35754051, 2022). "For patients with triple negative breast cancer, CCR3 was higher in Black versus White and CCRL2 was higher in Asian versus White." (PMID 35754051, 2022).